INS (insulin)
Diseases named in the same sentence as INS in open-access papers (continued):
Sharing a sentence is not in itself a finding about the gene and the disease.
Insulin resistance (continued). "One of the most frequent features of PCOS patients is the presence of increased insulin plasma levels as a compensation of insulin resistance, present in approximately 70–80% of women with PCOS and central obesity, as well as in 30–40% of lean women diagnosed with PCOS." (PMID 36009471, 2022). "Increased production of insulin in pancreatic β-cells, as a response to increasing insulin resistance, may function in the same way." (PMID 35742902, 2022). "Moreover, long-term insulin resistance prevents insulin from crossing the blood–brain barrier, leading to decreased insulin levels in the brain, which in turn impairs neuronal function and synaptic building." (PMID 36498726, 2022). "Fifth, we were not able to evaluate an association of reductions in insulin levels and improvements in insulin resistance with the risk of HF-related events in the CANDLE trial." (PMID 35941584, 2022). "Additionally, the role of CRP in the development of insulin resistance by affecting the insulin signaling pathway in hepatocytes, skeletal muscle, and endothelial cells has been described." (PMID 35883605, 2022). "Daily dosage of the insulin was similar; however, insulin resistance indices eGDR1 and eGDR2 were significantly lower in obese T1DM patients than in non-obese T1DM patients: eGDR1: 5.16 ± 1.33 vs. 6.96 ± 1.32; eGDR2: 9.37 ± 1.21 vs. 10.66 ± 0.9 (p = 0.0001, p = 0.0001), meaning insulin resistance." (PMID 36578961, 2022). "Insulin promotes apo B100 degradation, and hepatic insulin resistance reduces apo B100 degradation." (PMID 35203610, 2022). "It has been hypothesized that elevated insulin levels in the bloodstream are a result of insulin resistance, and that this increased insulin level may have a role in limiting spermatogenesis and male fertility." (PMID 36142487, 2022). "In type 2 diabetic conditions, there is a disturbed glucose uptake usually resulting in hyperglycemia and consequently increased insulin secretion, with time, that could result in insulin resistance." (PMID 36296534, 2022). "However, it is difficult to choose simple clinical parameters to reflect the extent of insulin resistance, especially in patients receiving insulin treatment." (PMID 36238131, 2022). "The animal study also showed that modulating insulin signal transduction cascades could alleviate the high-fat diet (HFD)-induced insulin resistance and CKD in obese rats." (PMID 35054932, 2022). "Stress-related hyperglycemia is associated with increased morbidity and mortality in critical illness, and IL-10 treatment has been shown to attenuate and prevent insulin resistance, improve insulin signaling, and beneficially affect peripheral glucose metabolism." (PMID 36243830, 2022). "Previous studies demonstrated that IL-6 triggers hepatic insulin resistance by inhibiting insulin signaling in vivo and in vitro and could thereby be involved in obesity-related hepatic insulin resistance." (PMID 35628414, 2022). "Similarly, elevated levels of TNF-α can disrupt insulin signalling through serine phosphorylation, thereby inducing insulin resistance in adipocytes and surrounding tissues and leading to the development of T2DM28." (PMID 36376474, 2022). "Surprisingly, cellular senescence did not cause insulin resistance, but rather robustly enhanced the insulin-stimulated phosphorylation of IR, Akt and MAPK, both in the absence and in the presence of oleic acid in the medium." (PMID 36072934, 2022). "Further, the improvement in insulin sensitivity was not related to the other traditional mechanisms underlying insulin resistance, including body fat distribution, adipose tissue and skeletal muscle function, and systemic inflammation." (PMID 36166072, 2022). "In addition, SREBP was found to be elevated in animal models with fatty liver and insulin resistance; moreover, despite insulin resistance in peripheral tissues, insulin was still able to activate SREBP in the liver, thus inducing downstream lipogenic enzymes." (PMID 36203751, 2022).
Insulin resistance (continued). "Patients who underwent long fasting periods (PS) had higher insulin levels in the first 24 hours (above reference values) compared to those who abbreviated their fasting for 2 hours before surgery (RL), which characterized an increase in insulin resistance." (PMID 35019120, 2022). "Several lines of evidence suggest that chronic activation of pro-inflammatory pathways in insulin target tissues, such as the adipose tissue, liver, muscle, and pancreatic islets may contribute to obesity, insulin resistance (IR), and T2DM." (PMID 35603204, 2022). "Finally, SCP on its own is unable to detect changes in insulin resistance (IR), insulin sensitivity (IS), insulin requirements, or changes in body weight." (PMID 35592786, 2022). "Evidence from in vivo and in vitro studies suggest that ADM could counteract insulin resistance through its antioxidant effects and the inhibition of insulin secretion." (PMID 35681200, 2022). "In older women, the degree of insulin resistance increases with a distinct reduction in physical activity because the hormonal imbalance after menopause results in increased adipose tissue accumulation, as well as increased fasting insulin and glucose levels." (PMID 36295873, 2022). "In addition, 5‐HT has been implicated in beta‐cell adaptive responses to pregnancy, with reports of enhanced insulin secretion and increased beta‐cell mass to compensate for peripheral insulin resistance." (PMID 35676820, 2022). "hypothesized that a decrease in insulin clearance could be the mechanism underlying higher irisin levels in individuals with increasing post-OGTT insulin levels, in the attempt to reduce β-cell stress due to increasing insulin resistance." (PMID 35774143, 2022). "DPP-4 inhibitors can inhibit glucagon secretion by increasing endogenous GLP-1 in patients and can be used in combination with insulin to improve insulin resistance, eliminate hyperglycemic toxicity altogether, complement the mechanism, and control glucose for a long time." (PMID 36015100, 2022). "In addition, obesity-related metabolic syndromes such as insulin resistance, insulin sensitivity and dyslipidemia were important factors in the pathogenesis of periodontal disease." (PMID 36131931, 2022). "Locally, molecular events involving inflammatory and redox alterations may impair the insulin signaling pathway, leading to insulin resistance." (PMID 35327570, 2022). "In contrast, while exosomes derived from M1 macrophages may induce insulin resistance, exosomes derived from M2 macrophages have been shown to enhance insulin sensitivity in liver, skeletal muscle and WAT both in vivo and in vitro." (PMID 36619588, 2022). "However, the diabetogenic pathomechanism of chronic HCV infection is not fully understood and involves both increased insulin resistance and reduced insulin secretion." (PMID 36168334, 2022). "The term ‘insulin resistance’ implies a reduced sensitivity of peripheral target tissues, which include adipose, muscle, and liver tissues, to normal circulating concentrations of insulin." (PMID 35883605, 2022). "For example, pinealectomized rats showed insulin resistance and glucose intolerance, and in Goto Kakizaki rats, a model for type 2 diabetes, nocturnal melatonin secretion was reduced whereas higher than normal levels of insulin were reported." (PMID 35455066, 2022). "Although insulin and Homeostatic Model Assessment of Insulin Resistance (HOMA-IR) levels are insignificantly higher in the cases than in the controls, the blood glucose levels are significantly higher in the pregnancy induced hypertension (PIH) group compared with the normotensive control group." (PMID 36558360, 2022). "Since insulin regulates the synthesis of these element-binding proteins too, fructose can indirectly stimulate their expression also by increasing insulin levels through its effect on insulin resistance." (PMID 35492316, 2022).
Insulin resistance (continued). "Although the natural history of T2D is described traditionally as a process of increasing insulin resistance followed by progressive insufficiency of insulin secretion, a primary genetic impairment of β-cell function has been hypothesized." (PMID 36614099, 2022). "The association was independent of DIo, a maker of insulin secretory capacity relative to insulin resistance." (PMID 36355105, 2022). "Acute stress hyperglycemia results from an increase in hepatic gluconeogenesis and liver glucose output even when endogenous insulin levels are high (central insulin resistance) and a lower uptake of glucose by insulin-dependent glucose transporters (peripheral insulin resistance)." (PMID 35578303, 2022). "Also others found less efficient BCAA reduction upon insulin infusion in obese humans with insulin resistance." (PMID 35931683, 2022). "To investigate whether systemic insulin resistance affected insulin signaling in the lungs, we analyzed expression levels of insulin receptors in the lungs by Western blotting." (PMID 35329973, 2022). "Consequently, the homeostatic index of insulin resistance (HOMA-IR) which is used to quantify insulin resistance was respectively reduced indicating a significant improvement in insulin sensitivity." (PMID 36575459, 2022). "Decreased subcutaneous as well as visceral adipose expression of SLC7A10 mRNA in insulin resistance was confirmed by directly comparing BMI-matched people with obesity who were either insulin resistant or insulin sensitive determined by hyperinsulinemic euglycemic clamp." (PMID 36172277, 2022). "Resistin, a cysteine-rich adipokine induced during adipogenesis, is proposed as a link between obesity and T2DM and may modulate numerous steps in the insulin-signaling pathway leading to insulin resistance and promote inflammatory processes." (PMID 35053667, 2022). "In these subjects, basal pro-NT is associated with the presence of an altered lipid profile, predicted weight gain, and the development of alterations in glucose-insulin metabolism, such as impaired β-cell function to compensate for insulin resistance later in life." (PMID 35216326, 2022). "Thus, a post-receptor binding defect in the insulin signalling pathway appears to play an important role in the aetiology of selective insulin resistance." (PMID 37361870, 2022). "Taken together, these preliminary results suggest that the rise in insulin may be secondary to the development of insulin resistance and a compensatory mechanism in the glucose regulation process." (PMID 36570168, 2022). "Both groups were assessed for waist circumference and underwent the following tests: fasting blood glucose, fasting insulin, high-density lipoprotein cholesterol level, and triglycerides, and homeostasis model assessment–insulin resistance (HOMA-IR) was applied." (PMID 36368970, 2022). "The pathophysiology of metabolic disease is complex, and there is variability in how obesity impacts insulin resistance and lipid metabolism, as some obese people remain insulin sensitive without associated cardiometabolic disorders." (PMID 36296997, 2022). "In addition, scientific evidence highlights IL-8 as a main adipocytokine producing insulin resistance via the inhibition of insulin-induced Akt phosphorylation in adipocytes." (PMID 35831885, 2022). "Taken together, inflammation induced by pro-inflammatory cytokines such as IL-6 and TNF-α is inversely correlated with insulin signaling where it might lead to insulin resistance." (PMID 36504710, 2022). "Also, the serum insulin level and homeostatic assessment of insulin resistance (HOMA-IR) were significantly higher in the 8-h." (PMID 36434695, 2022). "In line, levels of plasma adiponectin, an adipose tissue–secreted endogenous insulin sensitizer whose reduction is associated with insulin resistance, were not altered in tau KI mice." (PMID 35250480, 2022).
Insulin resistance (continued). "Diminished, insulin-stimulated glucose uptake in skeletal muscle is an indication of insulin resistance, due to defective insulin signaling and a number of intracellular post-receptor abnormalities, including reduced glucose oxidation and glycogen formation and impaired glucose transport." (PMID 36290804, 2022). "Generally, when insulin resistance occurs, islet β cell compensates for insulin insufficiency by increasing insulin secretion ability of individual cell or by proliferating, once pancreatic islet β cells fail to compensate for insulin resistance, hyperglycemia will be established." (PMID 35800345, 2022). "Moreover, the sample was categorized into two groups based on serum HOMA-IR, where <1 represents a higher degree of insulin sensitivity and ≥1 represents insulin resistance." (PMID 35889857, 2022). "The pathophysiology of glycemic dysregulation entails development of hepatic insulin resistance, which eventuates in fasting glucose elevations, and skeletal muscle insulin resistance and pancreatic beta-cell failure, which leads to post-prandial or post-load hyperglycemia." (PMID 35725477, 2022). "Obese patients with T2DM and significant insulin resistance may require as much as 1 IU of insulin for every 5 g of glucose while thin patients with T1DM may require only 1 IU for every 20 g of glucose." (PMID 36992742, 2022). "While studies directly relating insulin or insulin resistance to CAA are scarce, our data suggest that altered insulin homeostasis could be a mediator of the observed vascular alterations." (PMID 36345028, 2022). "Interestingly, adipose-specific Glut4 deletion decreased the insulin sensitivity of the muscle and liver, resulting in systemic glucose intolerance and insulin resistance." (PMID 34801552, 2022). "As expected, insulin resistance was identified in adiponectin KO mice and higher sensitivity to insulin resulting from P2Y4 loss was no longer observed in the absence of adiponectin in adiponectin/P2Y4 double-KO mice." (PMID 36532779, 2022). "In the presence of hepatic steatosis, various intermediate lipid moieties generated during triglyceride synthesis (e.g., diacylglycerols and ceramide) have been shown to promote lipotoxicity and enhance hepatic insulin resistance, likely by inhibiting insulin signaling pathways." (PMID 35432188, 2022). "Compared with the gold standard of euglycemic hyperinsulinemic clamp, fasting insulin, as measured with the Mercodia equine insulin ELISA, has been reported to have a sensitivity and specificity of 91% and 85%, respectively, for diagnosing insulin resistance using the cut-off of >9.5 of μU/ml." (PMID 35873691, 2022). "While there is limited knowledge about the molecular mechanisms underlying insulin resistance in PCOS, various studies have demonstrated how insulin signalling is impaired in the skeletal muscles, which are responsible for the insulin-resistance phenotype in PCOS women." (PMID 35052811, 2022). "The inability of insulin to perform cellular glucose uptake activity is termed insulin resistance, which may lead to onset of chronic conditions, such as obesity, cardiovascular complications and GDM in pregnant women." (PMID 36078079, 2022). "In contrast, old control males exhibited insulin resistance (sex x insulin interaction p < 0.01)." (PMID 35707855, 2022). "Type 2 diabetes is characterized by insulin resistance and deficient insulin secretion, although it does not develop only in response to insulin resistance." (PMID 35229479, 2022). "Fasting serum insulin and blood glucose levels were used to calculate insulin resistance." (PMID 36601507, 2022). "Propionate attenuated high-fat diet-induced insulin resistance and improved insulin sensitivity, and the mechanism of action might relate to stimulating OCFA production." (PMID 36140990, 2022).
Insulin resistance (continued). "The low-hanging fruits include translating education materials into local languages, developing a strategy to follow-up employed patients and using the lived experiences of insulin-treated patients to address insulin resistance and advocate for insulin therapy amongst PLWD and in communities." (PMID 35924623, 2022). "Insulin combined with hCG may destroy the normal pulse secretion mode of endogenous LH and is characterized by hyperandrogenism and insulin resistance." (PMID 36235780, 2022). "Abnormal insulin signals are the basis of insulin resistance, including insulin receptor degradation, excessive activation of protein tyrosine phosphatase, inflammation, and excessive stress-activated IKKbeta, JNK, ERK, S6K, and mTOR kinase, thereby inhibiting phosphorylation of IRS." (PMID 35224109, 2022). "Similarly, TRF intervention significantly reduced liver mass, fasting blood glucose, insulin, and insulin resistance index HOMA-IR." (PMID 36569870, 2022). "Simultaneously, reduced insulin signaling capacity and altered insulin receptors may factor into the increased insulin resistance reported in GDM." (PMID 36232232, 2022). "Furthermore, the induction of insulin resistance and elevation of circulating insulin in mice via disruption of the mTORC2 complex in adipocytes did not limit caloric restriction‐mediated lifespan extension." (PMID 35986566, 2022). "Interventions that reduce insulin resistance and the need for insulin secretion by pancreatic beta-cells, such as glucose-lowering medications (i.e., metformin) may also reduce the likelihood of prediabetes progressing to T2DM." (PMID 36432644, 2022). "In addition, LJF regulated the balance between insulin resistance and insulin sensitivity, reduced islet necrosis and β-cell damage, and inhibited fat accumulation in T2DM mice." (PMID 36613249, 2022). "In the present paper, we have shown that the addition of CM fruit extracts overcomes insulin resistance and increases glucose uptake after insulin stimulation in all experimental cell lines; however, a more favorable effect has been observed for red CM fruit extract." (PMID 35684107, 2022). "Reduced levels of hsCRP are reported among metformin users, a reduction that may be explained by the reduced insulin levels, as well as reduction in insulin resistance." (PMID 35300754, 2022). "Additionally, trigonelline was shown to have an insulin-sensitizing effect as measured by homeostasis model of insulin resistance (HOMA-IR) and homeostasis model assessment of β-cell function (HOMA-B)." (PMID 36432644, 2022). "Many insulin signaling genes were reprogramed by hyperinsulinemia, and this may contribute to the insulin resistance in our model." (PMID 34921686, 2022). "Blood glucose levels during pregnancy may reflect the severity of insulin secretory defects and/or insulin resistance during gestational diabetes mellitus (GDM) pregnancy." (PMID 34996380, 2022). "On the other hand, high maternal glycemia increases maternal insulin resistance, and the reduced insulin signaling may contribute to reduced fetal growth which triggers an increase in fetal adiponectin concentration." (PMID 34864815, 2022). "This approach identified the combinatorial effect of five etiological processes: insulin secretion (archetype A), obesity (archetypes B, C, and D), insulin resistance (archetypes C and D), dyslipidemia (archetypes C and D), and reduced β cell glucose sensitivity (archetype D)." (PMID 35106505, 2022). "LEP is involved in peripheral insulin resistance, impairs the action of insulin on insulin-responsive cells and may induce insulin resistance by affecting insulin secretion." (PMID 36005598, 2022). "We also wanted to measure common inflammatory response pathways that are known to attenuate insulin sensitivity in skeletal muscle in order to evaluate changes in cell signaling that could explain the insulin resistance observed." (PMID 36030929, 2022).